LINC01477 (long independently transcribed non-coding RNA 1477)
Gene: Long non-coding RNA gene on chromosome 18 (40,066,286 to 40,099,233, forward strand). Ensembl gene ENSG00000261715.
Diseases named in the same sentence as LINC01477 in open-access papers:
LINC01477 is named in the same sentence as 1 disease in open-access papers, as found by Europe PMC text mining. Sharing a sentence is not in itself a finding about the gene and the disease. The quoted sentences say what the papers report.
cancer (1 paper, 2024). A tumor composed of atypical neoplastic, often pleomorphic cells that invade other tissues. "Finally, there is a subset of LINC01378, LINC01443, LINC01477, and LINC01544, which are typically represented in one or two pathways in only one cancer type." (PMID 38540157, 2024).